VCAM1 (vascular cell adhesion molecule 1)
Diseases named in the same sentence as VCAM1 in open-access papers (continued):
Sharing a sentence is not in itself a finding about the gene and the disease.
atherosclerosis (continued). "VCAM-1 is an inducible endothelial cell surface molecule playing a role in mononuclear cell attachment, rolling, and transendothelial migration and is found to be important in both human and murine atherosclerosis." (PMID 23226424, 2012). "The data provide evidence for a direct involvement of GroEL1, which may enhance VCAM-1 expression in the endothelium and may mediate atherosclerosis progression." (PMID 22900050, 2012). "Furthermore, PAK activation in mouse arteries was observed specifically in atherosclerosis-prone sites and correlated with inflammatory gene expression, including vascular cell adhesion molecule-1 (VCAM-1)." (PMID 22824149, 2012). "Vcam-1 is an adhesion molecule that is expressed on activated endothelial cells and known to promote monocyte adhesion and accumulation on the vessel wall in the initiation stage of atherosclerosis." (PMID 20864429, 2011). "Inflammatory factors such as MCP-1 and VCAM-1 accelerate atherosclerosis in diabetic patients." (PMID 21350611, 2011). "VCAM-1 may be a specific marker for advanced atherosclerosis, since it is usually expressed on atherosclerotic plaques and VCAM-1 levels correlated with extent of atherosclerosis." (PMID 18955365, 2011). "VCAM-1 may be a more specific marker for advanced atherosclerosis, since it is usually expressed in atherosclerotic plaques and higher levels are associated with increased risk of coronary events in persons with existing CVD." (PMID 18955365, 2011). "VCAM-1 plays a more dominant role in atherosclerosis than ICAM-1." (PMID 22093181, 2011). "The ICAM-1 and VCAM-1 are important factors in the development of atherosclerosis and may play an important role in promoting the local inflammation within the atherosclerotic plaque." (PMID 21214952, 2011). "In corn-oil–fed mice injected with PCBs, VCAM-1 expression could even be detected in the sub-endothelial space, suggesting a progressed state of atherosclerosis with adhesion molecule expression on smooth muscle cells." (PMID 15626652, 2005). "Vascular cell adhesion molecule (VCAM)-1 has garnered significant research attention due to its potential as a disease biomarker and drug target across several inflammatory pathologies—including atherosclerosis, asthma, rheumatoid arthritis, and inflammatory bowel disease (IBD)." (PMID 40095109, 2025). "Based on these and other data, the authors hypothesised that endothelial injury in the early stages of atherosclerosis causes local release of nucleotides, which act at P2Y2R to produce lymphotoxin α, which in turn upregulates vascular cell adhesion molecule-1 expression, so promoting inflammation." (PMID 38740733, 2025). "Furthermore, SCFAs inhibit histone deacetylases (HDACs), particularly HDAC3, thereby downregulating vascular cell adhesion molecule-1 (VCAM-1) expression, which reduces monocyte adhesion to the endothelium and suppresses foam cell formation—a crucial step in atherosclerosis progression." (PMID 41373705, 2025). "However, VCAM1 expression can be upregulated in macrophages and many other cell types in inflammatory states, such as rheumatoid arthritis, cancer, transplant rejection, asthma, and atherosclerosis." (PMID 38690277, 2024). "Therefore, VCAM-1 expression within endothelial cells is thought to trigger atherosclerosis and it is well recognized that robust endothelial VCAM-1 expression predominantly occurs in atheroprone regions and atherosclerotic areas, but not in atheroresistant endothelial arterial cells." (PMID 37504271, 2023).
atherosclerosis (continued). "Furthermore, during atherosclerosis, macrophages in the artery wall might release Apoe and suppress vascular cell adhesion molecule 1 (VCAM-1) secretion, thus contributing to the inflammatory response." (PMID 36242090, 2022). "Since VCAM-1 expression is thought to precede the development of atherosclerosis and may be a major factor in determining where atherosclerotic plaques develop in the vasculature, we measured VCAM-1 expression in the coronary arteries of the mice in this study." (PMID 36714321, 2022). "However, a sudden change in shear stress can cause EC apoptosis by increasing secretion of proinflammatory factors [e.g., monocyte chemoattractant protein 1 and vascular cell adhesion molecule 1 (VCAM-1)] and is associated with several pathophysiological conditions (e.g., atherosclerosis)." (PMID 33898431, 2021). "Vascular cell adhesion molecule-1 (VCAM-1) expression is necessary for smooth muscle cell migration and proliferation, and is also involved in the phenotypic transformation of smooth muscle cells, playing an important role in the progression of atherosclerosis." (PMID 33791348, 2021). "Moreover, GATA6/VCAM-1 (a downstream target of miR-10a) was highly expressed in the endothelium, accompanied by the reduced levels of miR-10a during the development of human atherosclerosis." (PMID 34336268, 2021). "Given the vital role of G2A in the pathogenesis of inflammation and immune related diseases, and our previous studies that G2A regulates the LPC-induced expression of ICAM-1 and VCAM-1, we hypothesized that G2A may also be involved in the development of atherosclerosis." (PMID 34346841, 2021). "What is worse, the activated endothelia express adhesion proteins, such as vascular cell adhesion molecule-1 and E-selectin, attract leukocytes and activate platelets, altogether leading to elevated permeability of the endothelia and potentially the development of local atherosclerosis." (PMID 34394128, 2021). "Our findings suggest that low miR-10a and high GATA6/VCAM-1 in the cardiovascular endothelium correlates to the development of human atherosclerotic lesions, suggesting that miR-10a signaling has the potential to be developed as a biomarker for human atherosclerosis." (PMID 34336268, 2021). "Thus, VCAM-1 is an important cell adhesion molecule for the initiation of atherosclerosis." (PMID 34336268, 2021). "In the present study, we have tested the hypothesis that Romidepsin promotes the acetylation of non-histone proteins that regulate transcription leading to a downregulation of VCAM-1 expression by EC, which is of critical functional importance to atherosclerosis." (PMID 33859766, 2021). "In addition, it has been proposed that ICAM-1 may be predictive of cardiovascular events in adults, and VCAM-1 may be a prognostic factor in patients with atherosclerosis." (PMID 32433661, 2020). "Thus, VCAM-1-targeted MB have been proposed for atherosclerosis imaging." (PMID 32998422, 2020). "However, evidence has demonstrated that ICAM-1 deficiency substantially protects against atherosclerosis lesion formation in ApoE−/− mice, indicating a controversial issue, which is the dominate mediator between ICAM-1 and VCAM-1 in modulating atherosclerosis progression." (PMID 32472055, 2020). "However, their prevalence in atherosclerotic lesions is different: E-selectin is rarely expressed in atheromatous plaques (14% of cases); ICAM-1 is present in 46% of atherosclerotic lesions; and VCAM-1 is the most prevalent adhesion molecule in atherosclerosis (82%)." (PMID 33138124, 2020). "In atherosclerosis, the beginning stages of the development of an atherosclerotic lesion are characterized by endothelial cells beginning to express selective adhesion molecules such as vascular cell adhesion molecule-1 (VCAM-1) that promote attachment of leukocytes to the endothelium." (PMID 30791450, 2019).
atherosclerosis (continued). "VCAM-1 functions as a cell adhesion molecule, mediating the adhesion of lymphocytes, monocytes, eosinophils, and basophils to the vascular endothelium and may play a role in the development of atherosclerosis." (PMID 31778438, 2019). "Therefore, decreasing VCAM-1 expression might be beneficial in inhibiting inflammation and the development of atherosclerosis." (PMID 29875665, 2018). "In addition, we observed that serum soluble VCAM-1 and P-selectin levels, which play a major role in the initiation of atherosclerosis, were reduced and the expressions of MCP-1 and IL-6 in aortas implicated in mediating the pathogenesis of atherosclerosis were decreased by BM treatment." (PMID 30400958, 2018). "VCAM-1 is an important vascular (mainly endothelial) adhesion protein, which initiates the first step in the adhesion of circulating immune cells, followed by infiltration of these immune cells into adjacent tissues leading to the progression of atherosclerosis and unspecific tissue damage." (PMID 30647815, 2018). "Therefore, this study suggests that VCAM-1 plays a role in the pathogenesis of atherosclerosis." (PMID 26610475, 2015). "Hence VCAM-1 affects migration of SMCs in the intima and knockdown of this adhesion molecule could be a promising tool for treatment of atherosclerosis." (PMID 24276320, 2013). "Ultrasound molecular imaging is a low-cost, easily accessible screening method that has been shown to be feasible for the assessment of VCAM-1 expression during early atherosclerosis, and thus may allow for assessment of the adequacy of anti-inflammatory treatment in early atherosclerosis." (PMID 23554922, 2013). "Upregulation of cellular adhesion molecules like VCAM-1 and ICAM-1 has a close relationship with endothelial injury and dysfunction, which is the primitive phase of atherosclerosis." (PMID 40365513, 2025). "Increases SOD and GSH in serum in diseased mice.Suppresses the expression of IL-6, TNF-α, ICAM-1, VCAM-1 and NLRP3.Ameliorates atherosclerosis." (PMID 41300435, 2025). "Endothelial cells are pivotal in atherosclerosis pathogenesis, leading to the increased expression of adhesion molecules such as intercellular adhesion molecule 1 (ICAM-1) and vascular cell adhesion molecule 1 (VCAM-1)." (PMID 40809841, 2025). "Similarly, in a rabbit model of atherosclerosis, supplementation with jaboticaba (P. cauliflora) peel decreased plasma levels of IL-1β, IL-6, and soluble intercellular adhesion molecule-1 (sICAM-1) and soluble vascular cell adhesion molecule-1 (sVCAM-1) and reduced atherosclerotic lesions." (PMID 41375968, 2025). "Pro-inflammatory cytokines, such as TNF-α and IL-1β, contribute to atherosclerosis by inducing the expression of E-selectin, intercellular adhesion molecule 1 (ICAM-1), and vascular cell adhesion molecule 1 (VCAM-1) in endothelial cells." (PMID 41155632, 2025). "Endothelial dysfunction is a major contributor to atherosclerosis, and biomarkers such as intercellular adhesion molecule-1 (ICAM-1) and vascular cell adhesion molecule-1 (VCAM-1) provide insights into vascular inflammation and leukocyte adhesion." (PMID 40217801, 2025). "VCAM-1 and ICAM-1 mediate inflammation and promote leukocyte migration during inflammation, playing a crucial role in atherosclerosis as they facilitate the occurrence of cardiac events." (PMID 40002851, 2025). "In early stages of atherosclerosis, FSH/FSHR1 signaling, involved in the endothelial expression of VCAM1 upregulation, should have a positive role facilitating monocyte recruitment and diapedesis, a process beneficial for lipid clearance." (PMID 41024941, 2025). "Studies have shown that changes in shear stress can activate endothelial inflammation and increase the expression of cell adhesion molecules like VCAM-1 and ICAM-1, promoting atherosclerosis development." (PMID 40416982, 2025).
atherosclerosis (continued). "Endothelial cells of affected regions are activated and express high levels of adhesion receptors including vascular cell adhesion molecule 1 (VCAM-1), mediating adhesion of inflammatory cells which drive atherosclerosis development." (PMID 40403091, 2025). "Our findings indicate that lactate uptake into ECs via MCT1 increases vascular inflammation by upregulating VCAM‐1 and ICAM‐1, thereby contributing to atherosclerosis." (PMID 39949978, 2025). "Elmorsy et al20 found that 150 mg/kg/day N. sativa powder led to remarkable reduction in serum VCAM-1 and ICAM-1 levels in experimentally-induced atherosclerosis rabbits in comparison to the atherosclerosis control arm." (PMID 40365513, 2025). "We analyzed the expression levels of key atherosclerosis-related genes, namely ICAM-1, VCAM-1, iNOS, and LOX-1, to assess the molecular impact of bilirubin." (PMID 38982470, 2024). "Vascular endothelial cells have critical roles in atherosclerosis and after activation, they express adhesion molecules necessary for monocyte rolling and attachment (e.g., E-selectin, ICAM1 and VCAM1)." (PMID 39858417, 2024). "HDL can inhibit endothelial cell adhesion molecules, such as the vascular cell adhesion molecule 1 (VCAM-1), the intercellular adhesion molecule-1 (ICAM-1), and E-selectin, that enable monocytes to bind at the sites of developing atherosclerosis." (PMID 39594433, 2024). "Arterial lesions from both experimental atherosclerosis models and humans show increased expression of inflammatory biomarkers, such as MCP-1, E-selectin, ICAM-1, and VCAM-1." (PMID 39457059, 2024). "At the early stages of the inflammatory process in atherosclerosis, stimulation and local expression of ICAM-1 and VCAM-1 attract leukocyte recruitment and migration to inflammatory areas." (PMID 39457059, 2024). "OxLDL increased VCAM-1 protein expression which was suppressed by either olaparib or MCC950, consistent with their roles in the pathogenesis of atherosclerosis." (PMID 38335214, 2024). "The text-mining scores of VCAM1, which is a widely studied and well-known gene in CVD, in atherosclerosis, cardiovascular disease, endothelial dysfunction, dilated cardiomyopathy, were 0.876, 0.851, 0.799, and 0.627, respectively." (PMID 38177294, 2024). "One of the earliest steps of atherosclerosis is the recruitment of leukocytes by endothelial cells through the expression of adhesion molecules (such as ICAM-1 and VCAM-1) induced by IL-1β." (PMID 37476160, 2023). "Whilst both VCAM‐1 and ICAM‐1 are upregulated in atherosclerotic lesions, data indicates VCAM‐1 plays a predominant role in the initiation of atherosclerosis." (PMID 37457144, 2023). "Like the processes seen in atherosclerosis, nicotine upregulates ICAM-1 and VCAM-1, thereby recruiting leukocytes and activating the production of IL-1β by macrophages." (PMID 37476160, 2023). "Recently Yan and co-workers developed a microbubble targeting 3 markers (VCAM-1, ICAM-1 and P-selectin) which are the key players in atherosclerosis has given a new dimension to management of atherosclerosis." (PMID 36756211, 2023). "It has been well known that ICAM-1 and VCAM-1 play roles in arresting immune cells and initiating TEM, which plays an essential step in the development of atherosclerosis." (PMID 37228610, 2023). "During the development of atherosclerosis in HFD-fed ApoE-knockout mice, monocytes can migrate to the subendothelial space of the intima; this process is mediated by VCAM-1." (PMID 37764856, 2023). "Here, we found that IL-32θA94V mutant attenuated monocyte-endothelial adhesion, a critical early stage in atherosclerosis, by reducing the expression of ICAM-1 and VCAM-1." (PMID 37228610, 2023). "This was used to measure the metabolic activity of cells affected by atherosclerosis using nanobodies targeting various receptors such as macrophage mannose receptor (MMR), lectin-like oxidized LDL receptor (LOX), and VCAM-1." (PMID 37375810, 2023).
atherosclerosis (continued). "Therefore, VCAM-1 expression may play a major role in the initiation of atherosclerosis." (PMID 37947623, 2023). "TLR4 accelerates the progression of atherosclerosis and increases the expression of ICAM-1 and VCAM-1, leading to the synergistic activation of NF-κB in vascular walls in vivo and vascular smooth muscle cells in vitro." (PMID 35734399, 2022). "To validate the effect of APT1 on the H-Ras downstream signaling pathways, we measured the expression of p-ERK and its downstream atherosclerosis-related factors, such as MMP-9, VCAM-1, and ICAM-1." (PMID 35455042, 2022). "The authors then coated the VCAM-1–targeted MBs with miR-126-5p, which has been shown to inhibit VCAM-1 expression and atherosclerosis." (PMID 35135581, 2022). "Subsequently, genes related to the atherosclerosis indicators EDN1, PTGIS, AGT, NOS3, ICAM1, and VCAM1 were detected by qPCR." (PMID 36180828, 2022). "This process is accompanied by upregulation of vascular cell adhesion molecule-1 (VCAM-1) and intercellular adhesion molecule-1 (ICAM-1), and oxidized lipids and adhesion molecules mutually promote the plaque formation process of atherosclerosis." (PMID 36133804, 2022). "We have developed a molecular magnetic resonance imaging (MRI) tool to quantitatively report the inflammatory activity in atherosclerosis using dual-targeted microparticles of iron oxide (DT-MPIO) against P-selectin and VCAM-1 as a smart MRI probe." (PMID 34304360, 2022). "The cellular adhesion molecules (CAM), such as vascular cell adhesion molecule-1 (VCAM-1) and intracellular adhesion molecule-1 (ICAM-1) in blood vessels have a critical role in the progression of lesions in atherosclerosis." (PMID 35788200, 2022). "IS increased the expression of the adhesion molecules ICAM-1, VCAM-1, MCP-1, and e-selectin, all of which are involved in the pathophysiology of atherosclerosis." (PMID 35448889, 2022). "Meantime, the expression of pro-inflammatory factors, including intercellular adhesion molecule-1 (ICAM-1), vascular cell adhesion molecule-1 (VCAM-1), and interleukin-6 (IL-6) were increased, which led to vascular endothelial injury and atherosclerosis." (PMID 35935626, 2022). "Regulation of CAM proteins VCAM-1 and ICAM-1 will require a critical strategy to prevent and regulate chronic inflammatory disorders including atherosclerosis." (PMID 35788200, 2022). "In atherosclerosis, elevated expression of ICAM-1, VCAM-1, and selectins are essential markers of endothelial dysfunction." (PMID 36145277, 2022). "Atherosclerosis involves the formation of vascular lesions and the accumulation of inflammatory cells such as macrophages that express and upregulate cell surface receptors (e.g., vascular cell adhesion molecule-1, VCAM-1) that could be used as disease markers." (PMID 35163328, 2022). "Since the VHPK peptide (VHPKQHR) has high specificity and affinity to VCAM-1 on the endothelium in atherosclerotic plaque, the VCAM-1-targeting peptide, VHPK peptide, has been widely used for imaging and targeting the atherosclerosis lesion." (PMID 36293254, 2022). "TMAO furtherpromotes atherosclerosis by activating the CD36-dependent MAPK/Janus kinases(JAKs) pathway and triggering the expression of VCAM-1, TNF-α andIL-1β via the NF-κB pathway." (PMID 39077721, 2022). "In addition, preclinical data have suggested that canagliflozin might reduce infarct size, delay the progression of atherosclerosis, and downregulate the expression of adhesion molecules and inflammatory molecules, including vascular cell adhesion molecule-1 and monocyte chemotaxis protein-1." (PMID 34349651, 2021).